NEDD9 (neural precursor cell expressed, developmentally down-regulated 9)
Diseases named in the same sentence as NEDD9 in open-access papers (continued):
Sharing a sentence is not in itself a finding about the gene and the disease.
melanoma (continued). "Mesenchymal melanoma morphology and invasiveness style is controlled by a Rac1 activation pathway, mediated by adaptor protein NEDD9 and DOCK3, acting as a Rac1-GEF." (PMID 20822528, 2010). "Based on immunochemical staining of human melanoma tumor specimens, it was suggested that NEDD9 overexpression correlates with metastatic progression in human melanomas." (PMID 22545195, 2010). "Neural precursor cell expressed, developmentally down-regulated 9 (NEDD9) is another neuron-related marker expressed in melanoma." (PMID 22545195, 2010). "In addition, NEDD9 also significantly contributes to approximately one-third of the incidence of melanoma (36%) and its expression is upregulated and correlated with tumour progression." (PMID 36551688, 2022). "A complex of the GTPase RAC1-containing NEDD9 drives mesenchymal-type movement in melanoma cells." (PMID 34281234, 2021). "Abnormal expression of NEDD9 has been proved in colorectal cancer, lung cancer, and melanoma." (PMID 33344223, 2020). "These prompted us to examine whether SOX10 regulates NEDD9 expression in two metastatic melanoma cell lines (A375M and WM266–4) harboring mutated BRAF, which express high levels of SOX10 and NEDD9 expression." (PMID 30642390, 2019). "The predominant association of SOX10 and NEDD9 but not SOX9 expression in melanoma specimens is further supported by co-expression of these two factors at different levels in a series of malignant melanoma cell lines." (PMID 30642390, 2019). "Thus, we anticipated that SOX10 or high level of SOX9 regulates NEDD9 expression to promote melanoma migration through alteration of focal adhesion dynamics and RHO signaling activity." (PMID 30642390, 2019). "The transcription of miR-125b is induced by TCF4 (transcription factor 4), and one of the direct targets of miR-125b is a transcript of NEDD9 (neural precursor cell expressed developmentally down-regulated protein 9), which is involved in the mesenchymal movement of melanoma cells." (PMID 30866509, 2019). "Likewise, elevation of NEDD9 expression was detected in 30 to 50% of metastatic melanomas samples and promoted mesenchymal migration of melanoma cells through activation of RAC1 and inhibition of RHO/ROCK-driven amoeboid movement." (PMID 30642390, 2019). "RAC1 is involved in mesenchymal migration of melanoma cells, through the adaptor protein NEDD9." (PMID 31064137, 2019). "Moreover, there was no strict correlation between the patterns of SOX9, SOX10, and NEDD9 expression and distribution of pigmented melanomas in all examined stages." (PMID 30642390, 2019). "Whether NEDD9 expression is also subjected to the transcriptional regulation by SOXE proteins in melanoma remain to be determined." (PMID 30642390, 2019). "In vitro functional studies further showed that NEDD9 KD caused a marked reduction of cell growth, invasive behavior and colony formation capacity as observed in SOX10 KD, suggesting that NEDD9 is required for proliferation, invasion and oncogenicity of melanoma cells." (PMID 30642390, 2019). "In contrast, SOX9 expression began to express in a subset of NEDD9+ melanoma cells, which had metastasized to the small intestine and another subset of NEDD9+ cells exhibited SOX10 expression, whereas we detected co-expression of SOX10, SOX9, and NEDD9 in another patient with intestinal melanomas." (PMID 30642390, 2019). "Indeed, SOX9 OE at the highest titer (200 μL) in both SOX10 KD A375M and WM266–4 melanoma cells significantly restored the levels of NEDD9 mRNA and protein expression of both parental and phosphorylated forms compared to SOX10 KD alone." (PMID 30642390, 2019). "Altogether, our results demonstrate that SOX10 or high level of SOX9 expression could regulate focal adhesion dynamics and Rho GTPase signaling, partly through modulation of NEDD9 activity to promote mesenchymal migration of melanoma." (PMID 30642390, 2019).
melanoma (continued). "NEDD9 enhanced invasion in vitro and metastasis in vivo of both normal and transformed melanocytes, and was frequently overexpressed in metastatic melanoma relative to primary melanoma." (PMID 24743024, 2014). "NEDD9, an integrin adaptor protein related to P130CAS, and a member of a family implicated in pathogenesis of a variety of cancers, was identified as a bona fide melanoma metastasis gene in melanoma." (PMID 24743024, 2014). "NEDD9 enhances the invasion and metastatic potential in both melanocytes and melanoma." (PMID 22545195, 2010). "Increased levels of NEDD9 have been found in lung adenocarcinoma, glioblastoma, and melanoma." (PMID 20825672, 2010). "This is likely because SOX9 acting upstream of NEDD9 can regulate multiple downstream targets as previously demonstrated by RNAseq analysis, which revealed a few novel candidates that could potentially drive the invasive melanoma phenotype." (PMID 30642390, 2019). "NEDD9 enhanced invasion in vitro and metastasis in vivo of normal and transformed melanocytes, functionally interacted with focal adhesion kinase and modulated focal contact formation and exhibited frequent robust overexpression in human metastatic melanoma relative to primary melanoma." (PMID 23226728, 2012). "It has been shown that NEDD9 acted through SRC and STAT3 to promote invasion in melanoma, cervical cancer, and ovarian cancer." (PMID 34314382, 2021). "Consistently, as demonstrated in the functional assays, we found NEDD9 expression is regulated by SOX10 and mediates its metastatic functions in melanoma cell lines." (PMID 30642390, 2019). "AlamarBlue, transwell invasion and colony formation assays in melanoma cell lines were conducted to investigate the epistatic relationship between SOX10 and NEDD9, as well as the effects of graded SOX9 expression levels." (PMID 30642390, 2019). "In melanoma cells, ICAT competes with LEF1 to negatively regulate the M-MITF and NEDD9 target genes." (PMID 28273108, 2017). "In melanoma, two of the main targets of the Wnt/β-catenin pathway are the promoters of M-MITF and NEDD9 genes." (PMID 28273108, 2017). "In melanoma, TCF7L2 regulates the expression of NEDD9 through miRNA to affect tumor progression." (PMID 39060928, 2024). "We observed a significant reduction of NEDD9 transcripts in SOX10 KD compared to control, suggesting that NEDD9 expression could be regulated by SOX10 in melanoma cells." (PMID 30642390, 2019). "Compensatory upregulation of SOX9 expression in SOX10-inhibited melanoma cells reduced growth and migratory capacity, partly due to elevated expression of cyclin-dependent kinase inhibitor p21 and lack of NEDD9 induction." (PMID 30642390, 2019). "We revealed that further increased SOX9 dosage with comparable expression levels to a range of high SOX9 mRNA detected in malignant melanoma specimens could restore the metastatic properties in SOX10 knockdown cells, partly through induction of NEDD9 activity." (PMID 30642390, 2019). "To further determine whether SOX10 and/or SOX9 can regulate NEDD9 expression through transactivating its promoter, we performed luciferase reporter assay driven by the NEDD9 promoter (~ 1 kb) in both A375M and WM266–4 melanoma cell lines." (PMID 30642390, 2019). "Finally, NEDD9 overexpression increases motility and/or induces epithelial-to-mesenchymal transition (EMT) in melanoma, glioblastoma and breast or colorectal carcinoma cells in vitro." (PMID 29100287, 2017). "Previous studies showed that NEDD9 functions as an adaptor protein to assemble protein complex containing Src and FAK for inhibition of RHO/ROCK signaling in order to promote mesenchymal invasion of NC-derived melanoma cells." (PMID 29084958, 2017). "Moreover, immunohistochemical analysis has also revealed that NEDD9 overexpression is correlated with HNSCC and melanoma progression." (PMID 24058594, 2013).
melanoma (continued). "NEDD9 (also known as HEF1, Cas-L) is a scaffolding protein whose overexpression has been shown to promote cell growth, migration and invasion in a number of cancers like melanoma and glioblastoma." (PMID 23372733, 2013). "Likewise, overexpression of NEDD9 suggests poor prognosis in patients with colorectal cancer and promotes migration and progression of colon cancer cells through Wnt signaling, while SOX9 is known to mediate NEDD9 in melanomas." (PMID 31671847, 2019). "Whether SOX9 and/or SOX10 exhibit a similar regulatory relationship with NEDD9 in melanoma has not yet been examined." (PMID 30642390, 2019). "In addition, NEDD9, SOX9, and SOX10 have been shown to be crucial for human melanoma metastasis." (PMID 30642390, 2019). "Unlike NEDD9, p130Cas was not identified as a component of the metastatic signature of melanoma." (PMID 29876004, 2018). "Previous studies showed that NEDD9 exhibits both positive and negative roles in regulating focal adhesion dynamics and cell motility depending on the cellular context and also contributes to the mesenchymal-type of melanoma migration via modulation of small Rho GTPase activity." (PMID 30642390, 2019). "Immunofluorescence staining showed that NEDD9 was localized in the cytoplasm and co-expressed with most, if not all, of SOX10+ pigmented nevus and primary melanomas, whereas SOX9 was barely detectable." (PMID 30642390, 2019). "In this study, ICAT overexpression in melanoma cells was found to negatively regulate M-MITF and NEDD9 promoter activities, both in the presence and absence of ectopic LEF1." (PMID 28273108, 2017).
lung carcinoma (25 papers, 2011 to 2025). "Studies indicate that ISO decreases NEDD9, causing the suppression of cell growth, angiogenesis, invasion, and migration of human lung cancer cells." (PMID 40362444, 2025). "In accordance with this, previous studies have shown that NEDD9 actively suppresses autophagy in lung cancer cells, and that autophagy is enhanced in NEDD9-deficient cells." (PMID 40506423, 2025). "CRTC1 promotes LKB1-deficient lung cancer progression through NEDD9 transcriptional induction or glycosylated COX-2 protein activation." (PMID 40977688, 2025). "It is speculated that ISO downregulates NEDD9, causing upregulation of E-Cadherin, thus suppressing invasion and migration of lung cancer cells." (PMID 40362444, 2025). "ISO decreases the NEDD9 protein levels, causing the downregulation of HIF-1α and reduction in β-Catenin activation, leading to the inhibition of the malignancy of human lung cancer cells." (PMID 40362444, 2025). "This article for the first time demonstrates that NEDD9 supports glycolysis in lung cancer cells and tumors." (PMID 35410460, 2022). "The upregulation of NEDD9 promotes multi cancer metastasis, like epithelial ovarian cancer, epithelial ovarian cancer, lung cancers, hepatocellular carcinoma, and cervical cancer." (PMID 33344223, 2020). "The MALAT1/miR-145-5p/NEDD9 axis was described in lung cancer: MALAT1 sponges miR-245-5p to amplify NEDD9 expression." (PMID 31404273, 2019). "In the highly metastatic lung cancer cell line (H1792), stable LKB1 depletion caused increased migration in vitro and accentuated NRP-1 and NEDD9 expression in vivo." (PMID 26701889, 2016). "Expression profiling in human lung cancer cell lines has identified NEDD9 and CD24 as metastasis-promoting genes." (PMID 26418721, 2015). "Treatment of human lung cancer cells with ISO decreases NEDD9 protein levels." (PMID 40362444, 2025). "Overexpression of NEDD9 elevates the invasion and migration of human lung cancer cells." (PMID 40362444, 2025). "Moreover, NEDD9 expression regulated by miR‐145 was revealed in lung cancer, pancreatic cancer, renal cell carcinoma, prostate cancer and glioblastoma." (PMID 34432355, 2021). "Interestingly, another expression profiling study of human lung cancer cell lines and mouse lung tumors identified a variety of metastasis-promoting genes, such as VEGF, CD24, and NEDD9 as targets of LKB1 repression in lung cancer." (PMID 26056085, 2015). "FQ-PCR and western blotting revealed that the level of NEDD9 was markedly higher in A549 and 95D cancer cells, suggesting that NEDD9 might be involved in human lung cancer metastasis." (PMID 23226728, 2012). "Increasing the expression of NEDD9 may lead to an increase in lung cancer cell invasion ability." (PMID 23226728, 2012). "Furthermore, we have observed robust Dyn2 expression across endometrial and lung cancer specimens and cell lines, which appear to be independent of NEDD9." (PMID 26701889, 2016).
glioblastoma (19 papers, 2009 to 2021). The most malignant astrocytic tumor (WHO grade IV). "Recent research demonstrated that NEDD9 promotes the invasiveness of glioblastoma under the regulation of miR-145, and low expression of miR-145 in glioblastoma was associated with a more aggressive phenotype 92." (PMID 25124875, 2014). "NEDD9 increases the invasiveness of solid tumors such as gastric cancer, ovarian cancer, and glioblastoma." (PMID 30544746, 2018). "NEDD9 expression is elevated in tumor cell lines derived from epithelial lineages such as glioblastomas and lymphomas." (PMID 27974675, 2017). "A recent study also shows that miR-145 affects cell migration of glioblastoma (GB) in vitro and in vivo by directly targeting NEDD9, implicating an important role of miR-145 in GB invasion." (PMID 23710609, 2013). "To confirm the role of NEDD9 in glioblastoma invasion, we performed silencing experiments using the same cell lines used for miR-145 over-expression." (PMID 22869051, 2012). "Our results demonstrate the critical role of miR-145 and NEDD9 in regulating glioblastoma invasion and suggest a potential role of NEDD9 as a biomarker for glioma progression." (PMID 22869051, 2012). "In vitro NEDD9 silencing in GB-NS is responsible for the significant inhibition of invasion ability, thereby confirming the involvement of NEDD9 in glioblastoma invasiveness." (PMID 22869051, 2012). "NEDD9 is upregulated in response to retinoic acid in human neuroblastoma cells, regulates morphology in glioma and neuroblastoma, and has elevated expression and promotes survival and invasion in glioblastomas." (PMID 25594051, 2014). "Like NEDD9, PTK2B induces the migration and invasion of glioblastoma cells; a role that distinguishes it from its paralog FAK." (PMID 25594051, 2014). "NEDD9 is a necessary and specific downstream effector of focal adhesion kinase (FAK) that promotes the migration of glioblastoma cells." (PMID 23226728, 2012). "Moreover, our analyses revealed a downregulation of HEF1/NEDD9 and of metallo-matrixproteases pro-MMP1 and pro-MMP2 in SOX2-depleted U343-MG and U373-MG glioblastoma cells." (PMID 22070920, 2011).
colorectal cancer (11 papers, 2012 to 2023). A primary or metastatic malignant neoplasm that affects the colon or rectum. "Apigenin was observed to suppress cell migration and invasion in vitro and metastasis in vivo via downregulating the level of neural precursor cell expressed developmentally down-regulated protein 9 (NEDD9) in colorectal cancer." (PMID 34575983, 2021). "A previous study demonstrated that NEDD9 is highly expressed in the hypoxic areas of human colorectal cancer specimens." (PMID 31462898, 2019). "Taken together, our findings provided evidence that MLT+Ptero enhances apoptosis via miR-25-5p mediated NEDD9 inhibition in colon cancer cells as a potent strategy for colorectal cancer therapy." (PMID 31671847, 2019). "Given that overexpression of NEDD9 implies poor prognosis in colorectal cancer patients, we confirmed a dramatic effect of MLT (0.5, 1 mM) and/or Ptero (20, 40 μM) on NEDD and SOX10/9, especially in SW480 and HT29 CRCs better than in HCT116 cells." (PMID 31671847, 2019). "Taken together, our findings provide new insights that co-treatment of MLT and Ptero synergistically enhanced apoptotic effect via miR-25-5p mediated NEDD9 signaling in CRCs as a potent therapeutic strategy for colorectal cancer prevention or treatment." (PMID 31671847, 2019). "Human enhancer of filamentation 1 (HEF1, NEDD9, Cas-L), a scaffold protein implicated in cellular attachment and motility, is a mediator of HIF-1α-induced migration in colorectal carcinoma cells." (PMID 23241400, 2012). "MiR‐25‐5p directly targeting NEDD9 was found in oral squamous cell carcinoma and colorectal cancer." (PMID 34432355, 2021). "The inhibition of NEDD9 could induce cancer cell apoptosis in colorectal cancer." (PMID 33344223, 2020). "In a first study in colorectal cancer, PGE2 was shown to dramatically upregulate NEDD9 expression, raising the possibility that a COX2-PGE2-NEDD9 axis is also involved in AD." (PMID 25594051, 2014). "Similar as in our study, expression of NEDD9 was found significantly increased in the tissue of pancreatic ductal adenocarcinoma compared to adjacent pancreatic tissue, but the same was not established in colorectal cancer." (PMID 33485292, 2021).